SNORD38D (small nucleolar RNA, C/D box 38D)
Gene: Small nucleolar RNA gene on chromosome 8 (39,018,615 to 39,018,683, reverse strand). Ensembl gene ENSG00000207199.
Gene Ontology:
Biological process: RNA processing
Cellular component: nucleolus
Homologues: Orthologues: chimpanzee SNORD38D (100% identical), macaque SNORD38D (97% identical), rat Snord38b (83% identical), mouse Gm22980 (81% identical). Paralogues in human: SNORD38B (88% identical), SNORD38C (86% identical), SNORD38A (68% identical).